SP3P (Sp3 transcription factor pseudogene)
Gene: Processed pseudogene on chromosome 13 (89,361,160 to 89,363,224, reverse strand). Ensembl gene ENSG00000225530.
Diseases named in the same sentence as SP3P in open-access papers:
SP3P is named in the same sentence as 2 diseases in open-access papers, as found by Europe PMC text mining. Sharing a sentence is not in itself a finding about the gene and the disease. The quoted sentences say what the papers report.
glioma (2 papers, 2019 to 2022). A benign or malignant brain and spinal cord tumor that arises from glial cells (astrocytes, oligodendrocytes, ependymal cells). "Six pseudogenes (SP3P, ANXA2P3, PTTG3P, LPAL2, CLCA3P, and TDH) were reported to be associated with overall survival in glioma." (PMID 36333286, 2022). "A prior report that constructed another signature with six pseudogenes (SP3P, ANXA2P3, PTTG3P, LPAL2, CLCA3P, and TDH) for prediction of glioma patient survival." (PMID 31681595, 2019).
colon cancer (1 paper, 2023). "Interestingly, four genes that were originally highly expressed in the high SOCS3 expression group in colon cancer became low expressed after lung metastasis, including TTC40, PCDHA2, SP3P and ZNF471." (PMID 37025997, 2023).